IL6 (interleukin 6)
Diseases named in the same sentence as IL6 in open-access papers (continued):
Sharing a sentence is not in itself a finding about the gene and the disease.
COVID-19 (continued). "This study identified five blood markers (NMR, NLR, CRP, IL6, and DD) that were significantly associated with the risk of death in patients with COVID-19." (PMID 39555074, 2024). "Almost half of our cohort presented with IL-6 concentrations > 80 pg/mL, a prognosticating value associated with respiratory failure in patients with COVID-19." (PMID 36445625, 2024). "The cytokine IL-6 plays a key role in cytokine storm development and the pathogenic mechanism underlying COVID-19." (PMID 39516736, 2024). "Increased levels of IL-18 and its binding protein have been linked to the severity and progression of infectious diseases such as malaria while IL-1β and IL-6 are associated with sepsis and viral infections like COVID-19." (PMID 38251210, 2024). "Higher levels of creatine/creatinine were also associated with pro-inflammatory cytokines, such as IL-6, in subjects with severe COVID-19 and also with COVID-19 adrenal dysfunction and mortality." (PMID 39599883, 2024). "A metabolomic study on 33 patients with COVID-19 reported significant alterations in Trp metabolism in association with IL-6 in COVID-19 patients." (PMID 38802702, 2024). "Inflammation in COVID-19 is predictive of mortality and is associated with increased plasma concentrations of several cytokines including IL-2, IL-6, IL-7, IL-10, and TNF-α." (PMID 39345212, 2024). "Cytokine storms are associated with severe COVID-19, and many studies have reported that proinflammatory cytokines, such as interleukin (IL)-1, IL-6, and tumour necrosis factor, can be used as prognostic biomarkers." (PMID 38961438, 2024). "Patients with IL-6 levels exceeding 55ng/L were found to be at an increased risk of severe COVID-19, in while those with IL-6 > 80ng/L surpassing a greater risk of mortality." (PMID 38355623, 2024). "Clinical reports of COVID-19 patients show significant activation of T lymphocytes and monocyte-macrophages, leading to the expression of many cytokines, especially IL-6, further causing a cytokine storm and severe inflammatory reactions." (PMID 40376291, 2024). "COVID-19 patients suffered from severe lung injuries, respiratory distress, and higher mortality rates resulting from the cytokine storm caused by IL-6." (PMID 38966627, 2024). "STAT3 is a factor related to IL-6 and NF-KB, is known as an antiviral and proinflammatory mediator, and has been largely associated with COVID-19 disease severity." (PMID 38778280, 2024). "In this patient cohort, critical COVID-19 was associated with a significant increase in IL-6 concentration (p = 0.009)." (PMID 39518552, 2024). "In COVID-19 critical cases, a remarkable rise in the IL-6 level in blood was associated with sepsis or septic shock." (PMID 38672594, 2024). "Recent studies have demonstrated that the IL-6-JAK-STAT3 axis is closely associated with the severity of COVID-19." (PMID 39679195, 2024). "Consistent with a previous meta-analysis, it was also shown that the C allele of the − 174G > C SNP is linked to higher IL-6 production and more severe COVID-19 in the Caucasian population." (PMID 38783290, 2024). "Blocking pro-inflammatory cytokine IL-6 and upregulating the anti-inflammatory IL-10 reduces viral replication and decreases the systemic inflammation associated with COVID-19." (PMID 38612524, 2024). "According to systematic reviews and meta-analyses, elevated IL-6 levels were found to be associated with adverse clinical outcomes and severity of COVID-19." (PMID 39594223, 2024). "For the subgroup of diabetic patients hospitalized for COVID-19, the risk factors for death are: increased serum level of IL-6 and the development of infectious complications of any kind." (PMID 39252712, 2024). "The breakdown of neutrophil-derived serine proteases, IL-6, was suggested as a cause of less severe COVID-19 in PwCF." (PMID 38612524, 2024).
COVID-19 (continued). "Mainly, IL-6 levels have been linked to disease-related mortality in COVID-19-induced acute respiratory distress syndrome (ARDS) and the risk of severe pancreatitis." (PMID 38397885, 2024). "There is limited data about the role of IL-6 polymorphisms in pediatric COVID-19 and genetic background has been frequently ignored to be eventually confirmed as a major player in COVID-19 infection." (PMID 39354444, 2024). "The modulation of cytokines has been shown to be effective in infections with other pathogens, such as anti-interleukin-6 monoclonal antibodies, which play a beneficial role in the treatment of cytokine storms caused by COVID-19." (PMID 39460288, 2024). "It is reported that serum IL-6 levels are notably higher in severe cases of COVID-19, and these elevated IL-6 levels are strongly linked to worse clinical outcomes." (PMID 39595974, 2024). "Regarding inflammatory response, IL-6 has been described as an independent risk predictor for developing severe forms of COVID-19." (PMID 39637135, 2024). "To investigate the influence of variants in the promoter region of the IL-6 gene on the severity of COVID-19, we genotyped the − 597 A > G and − 174G > C polymorphisms in 132 patients with severe COVID-19 and 138 asymptomatic-moderate patients (mild cases)." (PMID 38783290, 2024). "COVID-19 viral infection compared to infection caused by other viruses is characterized by increased pro-inflammatory cytokine levels such as IL-6, IL-1β, and TNF-α." (PMID 39063142, 2024). "Reactive markers such as C-reactive protein (CRP), ferritin, and interleukin-6 (IL-6) have been associated with COVID-19 severity as well as other comorbidities." (PMID 39835130, 2024). "Interleukin-6 (IL-6) appears to be the key circulating cytokine associated with worse outcomes in COVID-19-related ARDS and predicts respiratory insufficiency significantly earlier than C-reactive protein (CRP)." (PMID 39274307, 2024). "This proinflammatory state, marked by high IL-6 levels, is linked to clinical deterioration and higher 60-day mortality in COVID-19 patients." (PMID 39518964, 2024). "A recent GWAS in a Chinese population (ncase = 632, ncontrol = 3021) reported an IL-6 down-regulating SNP in patients (rs2069837) to be protective against severe COVID-19 (OR = 0.41 for the G allele), contradicting our results." (PMID 39062668, 2024). "Meanwhile, an elevated level of IL-6 and IL-10 is associated with unfavorable prognosis for COVID-19 patients." (PMID 38173531, 2024). "Studies have also found that increased IL-6 levels are associated with tissue injury, hyperinflammation, and specifically more severe disease and progression to acute respiratory failure in COVID-19." (PMID 38539805, 2024). "The most significant association of genetically instrumented IL-6 was observed with COVID-19 hospitalization, i.e., HGI_ALL_B2 (OR (CI 95%) = 0.48 (0.30–0.76), p = 0.002)." (PMID 39062668, 2024). "Severe COVID-19 has been chiefly associated with inflammatory cytokines such as interleukin 6 (IL-6), IL-8, and IL-10 overexpression." (PMID 38375062, 2024). "Coronavirus disease-19 (COVID-19) is correlated to a severe condition caused by a cytokine storm during which numerous proinflammatory cytokines, including interleukin-6 (IL-6) are released." (PMID 39640429, 2024). "Consistent with prior studies, our findings corroborate the association between elevated IL-6 levels and adverse clinical outcomes, including prolonged hospital stays, complications, and mortality among COVID-19 patients." (PMID 39066228, 2024). "Elevated IL-6 levels in COVID-19 patients are linked to the significant depletion of CD4+ T cells, CD8+ T cells, and natural killer cells, contributing to the compromised immune response." (PMID 39518964, 2024).
COVID-19 (continued). "Elevated IL-6 levels play a pivotal role in cytokine storms associated with severe COVID-19, contributing to ARDS, multiorgan failure, and coagulation abnormalities, which manifest as increased thrombin generation and platelet activity." (PMID 39518964, 2024). "C-reactive protein (CRP), white cell count, and cytokines (CK) such as interleukin-6 (IL-6), IL-8, and IL-10 have been investigated as factors associated with the diagnosis or severity of COVID-19." (PMID 39654974, 2024). "Others showed positive associations between salivary viral load (VL) and COVID-19-related pro-inflammatory markers; IL-6, IL-18, IL-10, and CXCL1028." (PMID 39294156, 2024). "The cytokine storm and immunothrombogenesis have been implicated in the pathobiology of COVID-19, including excessive activation of the IL-1, IL-6, IL-8, complement, and coagulation pathways." (PMID 39459948, 2024). "The authors recommend monitoring and treating periodontal disease in patients with COVID-19 to potentially decrease IL-6 levels and reduce the risk of severe COVID-19 outcomes." (PMID 38800223, 2024). "Elevated levels of IL-6 are a significant indicator of the severity of COVID-19 and are closely associated with the increased mortality rate observed in patients." (PMID 39061002, 2024). "IL-6 gained wide recognition in the cytokine storm associated with COVID-19 and can now be measured using rapid kits using immunoassays." (PMID 38212363, 2024). "In previous studies, IL-6 and D-dimer have been identified as independent risk factors for the severity of COVID-19." (PMID 38822405, 2024). "One possible way of obtaining more knowledge on the topic is by studying genetic variants associated with IL-6 levels, or related signaling components, and their effects on COVID-19 outcomes." (PMID 39062668, 2024). "Coomes and Haghbayan conducted a meta-analysis revealing that IL-6 levels are 9.6 times higher in severe COVID-19 cases and are associated with adverse outcomes." (PMID 39281077, 2024). "Interleukin (IL)-6, known to be associated with adverse clinical outcomes in patients with COVID-19, is also a key cytokine in the tumor microenvironment." (PMID 38225613, 2024). "Diabetes and atrial fibrillation, as clinical factors, and LDH, IL-6 and lymphocyte count, as laboratory determinants, are the best predictors of COVID-19 mortality risk." (PMID 38982355, 2024). "Our study highlights the association of biomarkers such as CRP, serum ferritin, and IL-6 with renal injury in COVID-19 patients." (PMID 38975470, 2024). "For example, Ghazy (2023) discovered a significant correlation between the simultaneous presence of IL-8 rs2227306C and IL-6 rs1800795G alleles in an individual and an increased risk of severe COVID-19 outcomes." (PMID 38793070, 2024). "Localized inflammation observed during severe COVID-19 has been linked with respiratory distress and is also associated with elevated levels of cytokines, such as interleukin 6 (IL-6) produced by T cells and inflammatory monocytes." (PMID 38795859, 2024). "As expression of many of the pro-inflammatory cytokines implicated in COVID-19 is NF-κB-dependent, including IL-6, TNFα, and CXCL10 among others." (PMID 39882243, 2024). "In that context, some specific biomarkers, namely leukocyte count, fT3, and IL-6, have been found to be independent risk factors of worse prognosis in patients with COVID-19 admitted to the Internal Medicine department." (PMID 38243977, 2024). "Excessive production of interleukin-6 is associated both with more severe COVID-19 cases as well as with adverse pregnancy outcomes like preterm delivery, preterm premature rupture of the membranes, and chorioamnionitis." (PMID 39768627, 2024). "Consistent with previous findings and the established role of IL-6 as a hallmark inflammatory marker in COVID-19 patients, we observed a significant increase in IL-6 levels in patients compared to healthy controls during all pandemic waves." (PMID 39063569, 2024).
COVID-19 (continued). "IL-6 plays a central role in the cytokine storm seen in COVID-19 and influenza virus infections and is associated with severe disease outcomes." (PMID 39458339, 2024). "Increased levels of D-dimer, IL-6, pentraxin-3, and S100B were specifically associated with mortality in male critical COVID-19 patients only." (PMID 39507250, 2024). "The release of excessive levels of transforming growth factor (TGF), interferon (IFN), interleukin (IL)-1b, IL-6, IL-12, IL-18, and IL-33 is associated with COVID-19 causing changes in platelet indices, according to evidence in the literature." (PMID 39006704, 2024). "High IL-6 levels have been linked to severe COVID-19 and mortality, and, accordingly, has been proposed as a marker of disease progression." (PMID 39597537, 2024). "An elevated IL6 serum concentration is observed in patients with COVID-19 and is strongly associated with adverse clinical outcomes, suggesting it is a predictor of/linked to more severe disease." (PMID 38991709, 2024). "The so-called cytokine storm that characterized the most severe forms of COVID-19 was an exuberant inflammatory response associated with high levels of serum IL-6." (PMID 38731010, 2024). "Age, IL-6 levels, vaccination status, and comorbidities were independent predictors of serum IgG levels in asymptomatic or mild COVID-19 patients, facilitating risk stratification and clinical decision-making." (PMID 39717543, 2024). "Elevated IL-1β, IL-6, IL-8, IL-10, and IL-17 in plasma is associated with disease severity in COVID-19 patients." (PMID 39739157, 2024). "Conversely, individuals at moderate to severe risk of OSA with concurrent COVID-19 showed reduced levels of serum IL-6, Eotaxin-1/CCL11, and salivary MIP-3α/CCL20 compared to those with mild OSA risk and concurrent COVID-19." (PMID 38476500, 2024). "IL-6 is perhaps the most investigated cytokine in the context of COVID-19, and in line with our results, a large number of studies and several meta-analyses have concluded that increases in IL-6 levels are associated with COVID-19 severity and mortality." (PMID 38985797, 2024). "IL-6 signaling-related indicators such as IL-6, sIL-6R, and soluble gp130 (sgp130) were discovered to be prognostic and diagnostic predictors of COVID-19 illness." (PMID 39452786, 2024). "The mean calculated IL-6 concentration was approximately 5 pg/mL, which is consistent with values reported by other researchers for patients with mild to moderate COVID-19 symptoms associated with the omicron variant." (PMID 39338474, 2024). "Only IL-6 associations with severe COVID-19 outcomes reached the significance threshold corrected for multiple testing (p < 0.003; with COVID-19 hospitalization and critical illness)." (PMID 39062668, 2024). "Increased level of IL-6 is associated with severe form of COVID-19 and worsening viral disease on the cellular level." (PMID 39395941, 2024). "Nikhil Kirtipal and Shiv Bharadwaj, 2020 concluded that IL6 polymorphism is essential for understanding the treatment response to COVID-19 in infected humans and for developing population-based therapeutics." (PMID 39354444, 2024). "Recently, elevated serum IL-6 was found to be associated with respiratory failure, acute respiratory distress syndrome, and poor clinical outcomes in patients with COVID-19." (PMID 38672594, 2024). "COVID-19 has been associated with the excessive production of proinflammatory cytokines, such as IL-6, IFN γ, and TNF-α." (PMID 39407725, 2024). "In severe COVID-19, the ‘negative regulation of the insulin receptor pathway, inferred as a possible cause of IL-6 signalling and inflammatory responses, can lead to ‘insulin resistance’ and ‘increasing blood glucose level’." (PMID 38778394, 2024). "Among the pro-inflammatory cytokines, IL-6 is commonly considered the most important pro-inflammatory cytokine in terms of its association with the pathogenesis of severe COVID-19." (PMID 38935767, 2024).
COVID-19 (continued). "IL-6 is a critical marker for monitoring COVID-19 patients, as elevated IL-6 levels are associated with poor prognosis, including ICU admission, ARDS, respiratory failure, multiple organ dysfunction, shock, and increased mortality risk." (PMID 39493183, 2024). "An increase in IL-6 content is a risk factor for the severity of COVID-19 and mortality of affected patients." (PMID 39516736, 2024). "Meanwhile, other negative reports exist that fail to establish an association for IL-6 promoter SNPs with COVID-19 severity." (PMID 39062668, 2024). "Within these, inflammatory markers previously associated with COVID-19 severity were among the high-contribution features of the severity factor, including IL6, CXCL10, and CXCL8 (IL8) proteins in serum." (PMID 38690733, 2024). "Cytokines such as TNF-α (tumor necrosis factor), IL-6 (interleukin-6), and IL-1β are implicated not only in the inflammatory response to COVID-19 but also in the development of conditions like major depressive disorder and Alzheimer’s disease." (PMID 39767737, 2024). "This can lead to COVID-19-associated systemic inflammation and hypoxemic respiratory failure, as indicated by elevated blood levels of IL-6, C-reactive protein (CRP), D-dimer, and ferritin." (PMID 38251210, 2024). "Another study on an Amazonian population pointed to the presence of a consistent link between the polymorphisms of IL-6 and its receptor (IL-6R) with COVID-19 severity." (PMID 39452786, 2024). "One article also postulates that excessive interleukin-6 (IL-6) amplification can cause a cytokine storm after COVID-19 vaccination." (PMID 39628985, 2024). "Negative wellbeing is also associated with stress-induced elevations of inflammation, such as C-reactive protein, interleukin-6, fibrinogen, and white blood cell, which are biomarkers of critical COVID-19 and associated with mortality." (PMID 37213603, 2023). "Such evidence of an increase in levels of IL-6 is also associated with long COVID-19, which is defined after the time window of four weeks (≥ 28 days) post infection." (PMID 37095536, 2023). "Factors associated with IL-6 level after the administration of the Chinese COVID-19 inactivated vaccine." (PMID 36936962, 2023). "A recent study showed that low levels of CD4+T cells, high levels of IL-6, and inflammatory cytokines in COVID-19 patients increase the risk of severe liver injury." (PMID 36671484, 2023). "Acute COVID-19 was associated with marked elevations in nearly all pro-inflammatory markers, whilst eleven markers (namely IL-1β, IL-2, IL-6, IL-10, IL-18, IL-23, IL-33, TNF-α, IP-10, G-CSF and YKL-40) were associated with disease severity." (PMID 37063871, 2023). "We found that IL-6 was significantly associated with death by COVID-19 only during the first wave leading us to question the role of this cytokine as a single biomarker associated with fatal outcomes." (PMID 36817433, 2023). "CAM has recently gained attention as a rare but severe complication in COVID-19 patients, likely associated with the widespread use of corticosteroids, uncontrolled hyperglycemia, broad-spectrum antibiotics, and interleukin 6 inhibitors." (PMID 37623595, 2023). "Deceased COVID-19 patients were shown to have higher levels of IL-6 and CRP and were associated to poor clinical outcome and severe organ failure." (PMID 37545721, 2023). "IL-6 is critically involved in the COVID-19-induced cytokine storm and has been linked to the occurrence and progression of COVID-19 pneumonia in several investigations." (PMID 37143167, 2023). "The original levels of five cytokines were statistically significantly associated with COVID-19 mortality, i.e., IL-6 (p < 0.001), IL-2R (p < 0.001), IL-8 (p < 0.001), IL-10 (p < 0.001), and TNF-α (p < 0.05)." (PMID 37735372, 2023).